PPP2R3A (protein phosphatase 2 regulatory subunit B''alpha)
Description:
The B regulatory subunit might modulate substrate selectivity and catalytic activity, and might also direct the localization of the catalytic enzyme to a particular subcellular compartment.
Synonyms: PPP2R3; PR130; PR72
Tractability: PROTAC: ubiquitination databases record sites on it.
Gene: Protein-coding gene on chromosome 3 (135,965,655 to 136,147,894, forward strand). Ensembl gene ENSG00000073711.
Subcellular location (Human Protein Atlas): Golgi apparatus; Flagellar centriole; Mid piece
Gene Ontology:
Molecular function: protein binding; protein phosphatase regulator activity; calcium ion binding
Biological process: protein dephosphorylation; regulation of canonical Wnt signaling pathway; regulation of cell migration involved in somitogenic axis elongation; somatic muscle development; somite development; somitogenesis
Cellular component: protein phosphatase type 2A complex
Genetic constraint (gnomAD): Loss-of-function variants: 69 observed, 94.67 expected, observed/expected ratio (o/e) 0.73, 90% interval 0.6 to 0.89. The upper end of that interval is the gene's LOEUF score, 0.89, which puts it in group 3 of 6, group 1 being the genes least tolerant of losing a copy. Missense variants: 1,316 observed, 1,330.6 expected, observed/expected ratio (o/e) 0.99, 90% interval 0.94 to 1.03. Synonymous variants: 457 observed, 469.03 expected, observed/expected ratio (o/e) 0.97, 90% interval 0.9 to 1.05.
Homologues: Orthologues: chimpanzee PPP2R3A (99% identical), macaque PPP2R3A (95% identical), pig PPP2R3A (91% identical), dog PPP2R3A (91% identical), rabbit PPP2R3A (88% identical), guinea pig PPP2R3A (86% identical), mouse Ppp2r3a (86% identical), rat Ppp2r3a (85% identical), tropical clawed frog ppp2r3a (55% identical), zebrafish ppp2r3a (32% identical). Paralogues in human: PPP2R3B (26% identical).
Diseases named in the same sentence as PPP2R3A in open-access papers:
PPP2R3A is named in the same sentence as 36 diseases in open-access papers, as found by Europe PMC text mining. Sharing a sentence is not in itself a finding about the gene and the disease. The quoted sentences say what the papers report.
colon cancer (3 papers, 2013 to 2021). "We also identified 3 cancer-associated genes, GAN13, HBEGF, and PPP2R3A, with significantly decreasing expression levels in colon cancer (Group II)." (PMID 24564330, 2013). "PPP2R3A is highly methylated T- and B-acute lymphoblastic leukemia and colon cancers, resulting in the silencing of this gene in these cancer." (PMID 34072264, 2021).
dyslexia (3 papers, 2024 to 2025). A learning disorder characterized by an impairment in processing written words. "The top locus, chr3q22.2 (rs13082684, P = 1.8 × 10−21) containing PPP2R3A is consistent with the most highly associated SNP of the dyslexia GWAS." (PMID 40825760, 2025). "Our TWAS results validated the association between PPP2R3A and the common factor of dyslexia and rhythm impairment, and narrowed down the overall relevance of this gene for rhythm and reading skills into its expression profile in cerebellum and putamen." (PMID 39572686, 2025). "We found that several of the individual genetic loci that dispose most significantly to dyslexia were associated with the volumes of primary auditory cortices (Heschl’s gyri), including PPP2R3A, BCL11B, SATB2, and SH2B3." (PMID 39693421, 2024). "The most significantly associated independent SNPs; rs13082684 (PPP2R3A), rs2426117 (CSE1L) and rs9696811 (located between PTPA and IER5L), were consistent with loci reported in the univariate dyslexia GWAS." (PMID 40825760, 2025).
hepatocellular carcinoma (3 papers, 2019 to 2023). A malignant tumor that arises from hepatocytes. "Expression of PPP2R3A in tumor tissues of hepatocellular carcinoma (HCC) patients was detected by immunohistochemistry and western blotting." (PMID 31647192, 2019). "Further studies have found that PPP2R3A gene overexpression promotes HK1 levels and glycolysis, thereby promoting the proliferation, invasion and migration of hepatocellular carcinoma." (PMID 37124502, 2023).
liver cancer (3 papers, 2019 to 2024). An epithelial or non-epithelial malignant neoplasm that arises from the liver. "These include the B-type subunits PPP2R2D in gastric cancer and PR130 (encoded by the gene PPP2R3A) in liver cancer." (PMID 38570831, 2024). "Together, our results suggest that PPP2R3A may be associated with the occurrence of liver cancer via the regulation of tumor cell proliferation and invasion." (PMID 31647192, 2019). "Further research exploring the specific mechanism by which PPP2R3A affects the cell cycle progression and proliferation of liver cancer cells is required." (PMID 31647192, 2019). "Here we used the CCK‐8 assay to detect the effects of PPP2R3A knockdown on the proliferation of liver cancer cells." (PMID 31647192, 2019). "In the present study, we provide the first evidence of PPP2R3A protein expression in liver cancer and demonstrate its promoting effects on the proliferation and migration of liver cancer cells in vitro and in vivo." (PMID 31647192, 2019). "After 48 hours in culture following viral infection, a difference in the proliferation rates of liver cancer cells overexpressing PPP2R3A and the control cells appeared, with the cells overexpressing PPP2R3A exhibiting the higher proliferation rates (P < .05)." (PMID 31647192, 2019). "In contrast to the results obtained with PPP2R3A knockdown in liver cancer cells, the percentage of liver cancer cells in G1 phase was significantly decreased, while that in S phase was significantly increased (both P < .05)." (PMID 31647192, 2019). "To further confirm the role of PPP2R3A in the malignant behavior of liver cancer cells, we constructed a lentiviral vector for overexpression of PPP2R3A and infected Huh‐7 and HepG2 cells." (PMID 31647192, 2019). "To explore the potential role of PPP2R3A in liver cancer, we examined the expression of PPP2R3A via immunohistochemical staining in eight liver cancer tissue specimens from HCC patients." (PMID 31647192, 2019). "In vivo, PPP2R3A knockdown in liver cancer cells led to significant reductions in the tumor volume (P < .001) and the expression of Ki‐67 in tumor tissues (P < .05)." (PMID 31647192, 2019). "In the present study, we investigated the effect of PPP2R3A on the malignancy of liver cancer cells in vitro and in vivo, and our results provide evidence for the potential of PPP2R3A as a novel drug target for liver cancer therapy." (PMID 31647192, 2019). "Our staining experiment to detect PPP2R3A expression in liver cancer tissues showed that PPP2R3A protein was mainly located in the cytoplasm of HCC cells and partially expressed on the cell membrane." (PMID 31647192, 2019). "Next, we analyzed the effect of PPP2R3A knockdown on the in vivo proliferative potential of liver cancer cells based on the detection of Ki‐67 expression in tumor tissues harvested from the nude mouse models." (PMID 31647192, 2019). "Accordingly, the percentage of liver cancer cells in G1 phase was significantly increased after PPP2R3A knockdown, while that in S phase was significantly decreased (P < .05, P < .01)." (PMID 31647192, 2019). "In vitro, knockdown of PPP2R3A significantly inhibited liver cancer cell proliferation, while overexpression of PPP2R3A promoted liver cancer cell proliferation." (PMID 31647192, 2019). "Based on the observed effects of PPP2R3A knockdown on tumor cell growth in vitro and in vivo, we propose that PPP2R3A acts to enhance the proliferation of liver cancer cells." (PMID 31647192, 2019). "The results showed that PPP2R3A knockdown resulted in an obvious shift in the cell cycle of liver cancer cells, with their arrest in G1/S phase." (PMID 31647192, 2019). "Using the CCK‐8 assay, we found that PPP2R3A overexpression promoted liver cancer cell proliferation." (PMID 31647192, 2019). "To analyze cell cycle control progression following PPP2R3A knockdown in liver cancer cells, we detected the DNA content of the cells via flow cytometry after PI staining." (PMID 31647192, 2019).
liver cancer (continued). "The results showed that overexpression of PPP2R3A significantly changed the cell cycle distribution of liver cancer cells compared with the respective control cells." (PMID 31647192, 2019). "Using a Transwell assay, we assessed the effects of PPP2R3A knockdown on migratory and invasive potential of liver cancer cells." (PMID 31647192, 2019). "Conversely, overexpression of PPP2R3A promoted the proliferation (P < .05) and altered cell cycle progression (P < .05) of both liver cancer cell lines." (PMID 31647192, 2019). "Although we observed that knockdown or overexpression of PPP2R3A can affect the proliferation of liver cancer cells by affecting cell cycle progression, the related mechanism remains unclear." (PMID 31647192, 2019). "In conclusion, our present study showed that PPP2R3A plays an important role in the proliferation and invasion of liver cancer cells and may be a potential drug target for liver cancer therapy." (PMID 31647192, 2019). "To explore the effect of PPP2R3A gene knockdown on the malignant behaviors of liver cancer cells, we constructed two shRNA lentiviral vectors, namely shRNA‐PPP2R3A‐6328 (shRNA1) and shRNA‐PPP2R3A‐6332 (shRNA2), to infect two liver cancer cell lines, Huh‐7 and HepG2, individually." (PMID 31647192, 2019). "In two liver cancer cell lines (HepG2 and HuH7), PPP2R3A expression was silenced and then overexpression with PPP2R3A lentiviral vectors, and the effects of PPP2R3A knockdown or overexpression on the proliferation, cell cycle, migration, and invasion of HCC cells were determined in vitro." (PMID 31647192, 2019). "We found that Ki67 labeling index for tumor cells was significantly lower in the PPP2R3A knockdown (shRNA1) group than in the control group (P = .025), demonstrating that the knockdown of PPP2R3A inhibited the proliferation of the liver cancer cells in vivo." (PMID 31647192, 2019). "The results showed that at 48 hours after PPP2R3A knockdown, the proliferation of liver cancer cells was inhibited (P < .05) compared with that of control cells, and this difference in the proliferation rate continued to increase with more time in culture (P < .01)." (PMID 31647192, 2019). "To detect whether downregulation of PPP2R3A in liver cancer cells influences tumor growth in vivo, we constructed a xenograft tumor model in nude mice." (PMID 31647192, 2019). "These preliminary findings together with our results demonstrating the expression of PPP2R3A in the tumor tissues of liver cancer patients suggest that PPP2R3A may be a promising target for liver cancer therapy." (PMID 31647192, 2019). "This differential expression in HCC suggested that PPP2R3A may play a biological role in liver cancer." (PMID 31647192, 2019). "PPP2R3A may play a role in liver cancer via the regulation of tumor cell proliferation and invasion." (PMID 31647192, 2019). "The mechanism of PPP2R3A's role in liver cancer warrants further attention." (PMID 31647192, 2019). "After 48 hours of virus infection, fluorescence microscopy revealed that the infection rates of the two liver cancer cells were both above 90% (data not shown), and the knockdown effect on PPP2R3A expression was detected by qRT‐PCR and western blotting." (PMID 31647192, 2019).
coronary artery disease (2 papers, 2023). "Other genomic studies have also demonstrated an association between the PPP2R3A gene and cardiomyopathy and coronary artery disease in humans." (PMID 37868783, 2023). "Moreover, we prudently excluded three SNPs, namely rs1260326 in GCKR, rs34894639 in PPP2R3A, and rs2943652 in NEU2, owing to their known pleiotropic effects on a range of human traits, including T2DM, coronary artery disease, BMI, and triglycerides, as evidenced by PhenoScanner database searches." (PMID 37049421, 2023).
heart failure (2 papers, 2016 to 2023). Inability of the heart to pump blood at an adequate rate to meet tissue metabolic requirements. "PPP2R3A is in turn a component of the Wnt signaling pathway, which is linked to cardinal fibrosis, myocardial infarction, and heart failure." (PMID 37868783, 2023). "Previous research has implied that PPP2R3A was involved in heart failure, and PR130, the largest transcription of PPP2R3A, functioning in the calcium release of sarcoplasmic reticulum (SR), plays an important role in the excitation-contraction (EC) coupling." (PMID 27845735, 2016). "PPP2R3A that belongs to the regulatory subunit B family of PP2A has been reported to be located on both Z- and M-lines in myocardium and to be involved in heart failure." (PMID 27845735, 2016).
prostate carcinoma (2 papers, 2018 to 2025). A carcinoma that arises from epithelial cells of the prostate gland. "This reduction is abrogated upon addition of anti-miR-652 (p < 0.05), further verifying that PPP2R3A is indeed a direct target of miR-652 in prostate cancer cells." (PMID 29721191, 2018). "The inhibition of both luciferase activity and PPP2R3A expression by miR-652 was blocked by miR-652 antagomir, further verifying that PPP2R3A is indeed a direct target of miR-652 in prostate cancer cells." (PMID 29721191, 2018). "In contrast, miR-652 expression in LNCaP prostate cancer cells induced NED through a pathway initiated by PPP2R3A inhibition, resulting in increased AKT, ERK-1/2 and Wnt activation, loss of AR, with gene transcription via activated β-catenin." (PMID 29721191, 2018). "We show that miR-652 inhibits the expression of PPP2R3A in prostate cancer cells and xenografts." (PMID 29721191, 2018). "In conclusion, our data indicate that miR-652 is a novel oncomiR in prostate cancer cells, inhibiting PP2A activity, through direct targeting of the PP2A regulatory subunit, PPP2R3A." (PMID 29721191, 2018).
pulmonary fibrosis (2 papers, 2022 to 2023). Chronic progressive interstitial lung disorder characterized by the replacement of the lung tissue by connective tissue, leading to progressive dyspnea, respiratory failure, or right heart failure. "Based on accumulating evidence, the migration, proliferation and activation of lung fibroblasts are the main causes of pulmonary fibrosis, and thus, the effect of PPP2R3A on these cellular functions was investigated in HPF-a cells." (PMID 35933397, 2022).
dilated cardiomyopathy (1 paper, 2023). Cardiomyopathy which is characterized by dilation and contractile dysfunction of the left and right ventricles. "For instance, PPP2R3A expression is reduced in a mouse model of dilated cardiomyopathy." (PMID 37868783, 2023).
endometrial cancer (1 paper, 2019). Primary or metastatic malignant neoplasm involving the endometrium (mucous membrane that lines the endometrial cavity). "Among these survival-related genes, five genes (EPHB2, FBP1, NLRC3, PPP2R3A, and TRIM46) were included in a previously reported 9-gene signature for predicting endometrial cancer patient survival." (PMID 30847026, 2019).
hypertrophic cardiomyopathy (1 paper, 2023). A condition in which the myocardium is hypertrophied without an obvious cause. "Additionally, the study identified potential candidate genes, such as COL1A2 and BCL6, which interact with PPP2R3A and are also believed to play a role in the progression of myocardial infarction and hypertrophic cardiomyopathy or in tumor development." (PMID 37868783, 2023).
ischemia (1 paper, 2018). A hypoperfusion of the BLOOD through an organ or tissue caused by a PATHOLOGIC CONSTRICTION or obstruction of its BLOOD VESSELS, or an absence of BLOOD CIRCULATION. "The alpha regulator subunit B'' of protein phosphatase 2 (PPP2R3A), a regulatory subunit of protein phosphatase 2A (PP2A), was reported to present a special subcellular localization in cardiomyocytes and elevate in non-ischemia failing hearts." (PMID 30481179, 2018).
kidney stones (1 paper, 2024). "Notably, genes PPP2R3A for BUN, VAMP8 for UACR, DOCK7 for creatinine, and HIBADH for kidney stones were identified as shared risk genes by all three methods." (PMID 39086896, 2024).
pulmonary arterial hypertension (1 paper, 2021). Pulmonary arterial hypertension (PAH) is a group of diseases characterized by mean pulmonary artery pressure >20 mmHg and elevated pulmonary arterial resistance leading to right heart failure. "Therefore, it is likely that the reduced expression of PP2A regulatory subunits, in particular Ppp2r3a, may account for the impaired PP2A activity observed by the previous study in PASMCs from patients with pulmonary arterial hypertension." (PMID 34635097, 2021).
silicosis (1 paper, 2022). Silicosis is a respiratory disease caused by breathing in (inhaling) silica dust. "The GREM1/PPP2R3A pathway may be a potential target in the early treatment of silicosis." (PMID 35933397, 2022). "Inflammatory-proliferative fibroblasts play a key role in the early pathological changes that occur in silicosis, and during this process, GREM1 is the driving factor that targets PPP2R3A and initiates the inflammatory response, which is followed by irreversible fibrosis induced by SiO2." (PMID 35933397, 2022).
tongue cancer (1 paper, 2015). A malignant neoplasm affecting the tongue. "After comparison between tongue cancer and corresponding normal samples, GNA15, PPP2R3A, LAMB3, HSPA2, and MAP4K3 were identified as five top-ranking genes." (PMID 26336805, 2015).